SIRT1 (sirtuin 1)
Diseases named in the same sentence as SIRT1 in open-access papers (continued):
Sharing a sentence is not in itself a finding about the gene and the disease.
Hypertension (continued). "Hypertension programmed by a maternal methyl-donor diet is related to decreases in several forms of nutrient-sensing signaling, including Sirt1, Prkaa2, Pparb, and Pparg." (PMID 31766163, 2019). "This is consistent with our recent report showing that resveratrol, a known AMPK activator, protects against maternal combined with post-weaning high-fat diets-induced hypertension via increasing SIRT1 and AMPKα2." (PMID 29641494, 2018). "We previously found that resveratrol, a known natural activator of AMPK, prevents the combined maternal plus post-weaning high-fat-diets-induced hypertension related to increased protein levels of SIRT1 and AMPKα2." (PMID 29614026, 2018). "In a recent study, the exogenous TPRV4 activator apigenin reduced hypertension-induced renal fibrosis through the AMP-activated protein kinase/sirtuin 1 pathway in a deoxycorticosterone acetate (DOCA)–salt rat model." (PMID 29559678, 2018). "In mice without endothelial nitric oxide synthase, selective overexpression of human SIRT1 in endothelium prevents hypertension and age-related adverse arterial remodeling." (PMID 27259994, 2016). "These recent studies point to the potential of therapeutically improving SIRT1 function in VSMCs to treat hypertension." (PMID 27037223, 2016). "Relationship between exercise/training/activity and FOXO proteins: Exercise training combined with VH-4 peptide treatment increased the expression of FoX3α through AMPKα1, Sirt1, and PGC1α signaling pathways, improving cell survival and reducing hypertension-induced damage." (PMID 40861274, 2025). "Moreover, when administered with a selective SIRT1 activator known as SRT1720, arterial stiffness and hypertension were eliminated via Klotho loss in mice muscle cells KL+/−." (PMID 41567643, 2025). "Additionally, mice models with SIRT1 knockout (SIRT1+/−) exhibit typical pre-eclampsia-like symptoms, such as hypertension, proteinuria, fetal growth restriction, renal injury, and narrowing of placenta's labyrinth layer." (PMID 38448466, 2024). "We hypothesized that EA may alleviate neuroinflammation and oxidative stress, reduce sympathetic outflow, and alleviate hypertension by inhibiting SIRT1 expression." (PMID 39234603, 2024). "Furthermore, resveratrol has been shown to downregulate AGTR1 expression via SIRT1 and has beneficial effects on hypertension." (PMID 39273282, 2024). "Research on arsenic-induced hypertension suggested that MT may exert a protective effect against arsenic-induced vascular toxicity by suppressing apoptosis and modulating the Sirt1/autophagy pathway." (PMID 39331788, 2024). "Extracellular vesicles collected from induced pluripotent stem cell-derived mesenchymal stem cells, may reduce age-related endothelial dysfunction, arteriosclerosis, and hypertension by activating the SIRT1-AMPKα-eNOS pathway." (PMID 36632457, 2023). "Grape seed proanthocyanidin extracts (GSPE) indirectly up-regulates SIRT1 and inhibits aortic NO production disorder, improving hypertension and showing the potential of anti-inflammatory, antioxidant, anti-ageing and regulation of endothelial function 115-117." (PMID 36632457, 2023). "In reduced uterine perfusion pressure (RUPP) rats, constituting an animal model of PE, supplementation with recombined SIRT1 protein alleviates PE manifestations, such as arterial hypertension, impaired placental angiogenesis, inflammatory response, and unfavorable pregnancy outcome." (PMID 38003402, 2023). "A clinical study revealed a significant correlation between a polymorphism (rs2273773) of the SIRT1 gene and dynamic blood pressure levels in patients with hypertension of the Kazakh ethnic group, indicating a potential link between SIRT1 and blood pressure regulation." (PMID 37754811, 2023). "For the purposes of this study, we hypothesized that, in cases of hypertension, SIRT1 would regulate ROS levels through the NF-κB pathway in the PVN." (PMID 36235829, 2022).
Hypertension (continued). "In the study, we hypothesized that ARB might prevent cardiac Fas/FasL-mediated to mitochondria-mediated apoptotic pathways and enhance the cardiac SIRT1/PGC-1α pro-survival pathway in hypertension." (PMID 36005430, 2022). "In summary, this study explored the hypothesis that administration of resveratrol in the PVN would attenuate high blood pressure via the SIRT1/NF-κB pathway, by regulating ROS and neurotransmitters during hypertension." (PMID 36235829, 2022). "The dual AT1R blockers/PPAR-γ agonist ARB could prevent apoptotic progression through the upregulation of the cardiac SIRT1/PGC-1α pro-survival pathway associated with IGF-II and p-JNK deactivation in hypertension." (PMID 36005430, 2022). "Additionally, SIRT1 knockdown (SIRT1+/−) mice showed typical pre-eclampsia-like symptoms, such as hypertension, proteinuria, fetal growth restriction, kidney injury, and a narrowed placental labyrinth layer." (PMID 35327614, 2022). "We determined that C. cicadae or RES downregulates p62 and disrupts relative expression of beclin-1 and LC3II, indicating that C. cicadae controls hypertension-induced autophagic stress by restoring SIRT1 levels in order to inhibit the development of renal fibrosis." (PMID 35222012, 2021). "A combination of SIRT1 agonists and angiotensin II antagonists may be considered for use in the treatment of hypertension, especially the renovascular type." (PMID 34730891, 2021). "In addition, previous study shows that patients with arterial stiffness and hypertension had reduced serum levels of SIRT1 compared to normal subjects." (PMID 33324265, 2020). "The mixture of RSV/QSC reversed hypertension caused by short- and long-term exposure to sucrose by modifying the expression of eNOS, the antioxidant capacity, and the expression of SOD2, and increased the expression of SIRT1 in the aortas of MS rats." (PMID 32210194, 2020). "The deficiency of Klotho, predominantly expressed in the kidney and recognized as an aging-related molecule, could stimulate arterial stiffness and hypertension along with repressed aortic SIRT1 expression in mice." (PMID 33117155, 2020). "Moreover, resveratrol treatment activated SIRT1, resulting in the repression of Ang II type 1a receptor gene transcription to counteract Ang II-induced hypertension in mice." (PMID 27037223, 2016). "Additional adjustment for traditional cardiovascular risk factors and markers (BMI, smoking status, hypertension, total cholesterol, HDL-cholesterol, hsCRP) even improved the strength of this association (p = 0.0037 for SIRT1 and p = 0.0002 for both SNPs at FOXO1)." (PMID 25273948, 2014). "In addition to its potent cardioprotective properties, cardiac-restricted mIGF-1 transgene induced systemic changes such as high blood pressure, leukocytosis and an enhanced fear response, in a SIRT1-dependent manner." (PMID 22691943, 2012). "However, it remains unclear whether SIRT1 has any effect on hypertension in the central nervous system." (PMID 36235829, 2022). "Therefore, whether SIRT1/PGC-1α signaling is involved in the regulatory effect of ARB on mitophagy or mitochondrial dynamics is unknown in the pathogenesis of hypertension-induced cardiac dysfunction." (PMID 36005430, 2022).
Hypertension (continued). "As angiotensin II increases in the acute phase of this type of hypertension, and angiotensin II and SIRT1 counteract the expression of each other, SIRT1 reduction in the heart and kidney along with the influence of angiotensin II may take part in the establishment of hypertension." (PMID 34730891, 2021). "Hence, pharmacological activation of SIRT1 may be an effective therapeutic strategy for hypertension and hyperlipidemia, and the SIRT1 activator resveratrol further confirmed this hypothesis." (PMID 33324265, 2020). "Based on the increments of glutathione disulfide (GSSH), SOD, Ac-FOXO1, GSH, SIRT1, Nrf2, HO-1, and NQO-1, genistein inhibited oxidative stress through the SIRT1/Nrf2 pathway, providing a basis for high-salt diet-induced hypertension treatment." (PMID 40867803, 2025). "Upregulating the expression of SIRT1 in the PVN of SHRs reduces NF-κB p65 activity, inhibits inflammasome formation, thereby weakening sympathetic nervous activity, and alleviating hypertension." (PMID 39234603, 2024). "It has been reported that activation of SIRT1 suppressed AT1R expression and enhanced NO bioavailability, thereby ameliorating hypertension in mice." (PMID 39592923, 2024). "In this context, GS and BS patients, in comparison to healthy individuals, sustain higher levels of sirtuin-1 (SIRT1) activity, which seems to have a significant impact on hypertension and the aging process." (PMID 39273282, 2024). "The overexpression of NAMPT partially inhibits Ang II-induced elevated ROS levels by regulating SIRT1 and the concentration of NAD+, thus relieving Ang II-induced hypertension." (PMID 36632457, 2023). "SIRT1 and AMPK can, respectively, deacetylate and acetylate PGC-1α, to mediate PPARs and their target genes, thereby resulting in hypertension later in life." (PMID 35624788, 2022). "Both bioactive peptide VH-4 and exercise training alleviate hypertension-induced histological changes, activating PI3K/AKT cell survival pathway and AMPKα1, Sirt1, PGC1α, and FoX3α pathway." (PMID 36431802, 2022). "Mitochondrial dysfunction and the inhibition of energy metabolism‐related proteins, AMP‐activated protein kinase (AMPK) and Sirtuin 1/3 (SIRT1/3), play an important role in the progression of hypertension." (PMID 34331512, 2021). "Overexpression of SIRT1 in murine endothelial cells prevented hypertension and adverse arterial remodeling; however, a knockdown of HERC2 abolished any beneficial effects of SIRT1, suggesting a neuroprotective regulatory role of HERC2." (PMID 34252155, 2021). "Results of the current study go beyond previous reports, showing that therapeutic use of direct AMPK activator AICAR in lactation activated AMPK/SIRT1/PGC-1α pathway and prevented the development of hypertension concurrently." (PMID 32053935, 2020). "Conversely, activation of the AMPK/SIRT1/PGC-1α pathway can reverse the programming process and prevent hypertension in adult offspring." (PMID 32545526, 2020). "Our results demonstrated that maternal DMF therapy activate several nutrient sensing signals—including SIRT1, AMPKα2, and PGC-1α—by which it protects adult male offspring against hypertension." (PMID 31416234, 2019). "In contrast, prenatal metformin therapy did not activate but rather inhibited AMPK-related nutrient sensing signals, including AMPKs, SIRT1, SIRT4, PPARs, and PGC-1α, by which it protects adult male offspring against hypertension." (PMID 29614026, 2018). "In addition, the novel role of Sirt1, Sirt4 and ANXA1 in hypertension related bone marrow microvascular ageing deserves further study." (PMID 41507140, 2026). "PE symptoms, like hypertension, proteinuria, fetal growth restriction, and kidney injury, were observed in SIRT1-knockdown mice, and these symptoms improved upon administration of SRT2104, an allosteric activator that binds to the N-terminus of SIRT1." (PMID 41471349, 2025).
Hypertension (continued). "In conclusion, EMPA might exert vasoprotective effects in hypertension by enhancing endothelium-dependent relaxation and reducing constriction via AMPK/SIRT1 pathways." (PMID 40214461, 2025). "Our analyses showed that TNF, HSP90AA1, NFKB1, PPARG, SIRT1, PTGS2, and RELA might be α-MG’s potential therapeutic targets for hypertension, laying groundwork for further investigation into its pharmacological mechanisms and clinical uses." (PMID 39592923, 2024). "SIRT1 (sirtuin 1), one member of SIRTs (class III histone deacetylase) that are highly conserved NAD+-dependent deacetylases, plays a vital role in the pathogenesis of hypertension." (PMID 37501791, 2023). "DF peptides and exercise act synergistically and attenuate the myocardial injury induced by spontaneous hypertension, possibly by regulating the energy metabolism signaling pathway (AMPK/SirT1/PGC-1α/FOXO3), as well as preventing myocardial fibrosis, hypertrophy, and apoptosis." (PMID 35890118, 2022). "Several nutrient-sensing signals are involved in the early life origins of hypertension, including AMP-activated protein kinase (AMPK), peroxisome proliferator-activated receptors (PPARs), silent information regulator T1 (SIRT1), and PPARγ co-activator 1α (PGC-1α)." (PMID 35624788, 2022). "In the current study, we hypothesized that exercise and DF administration might ameliorate hypertension in the SHR model and, if so, the anti-hypertensive effects of DF and exercise may be partly due to the regulation of the AMPK/SIRT1/PGC-1α/FOXO3 pathway." (PMID 35890118, 2022). "Given that AMPK and SIRT-1 can mediate the expression of PPAR target genes, and that several PPAR target genes contribute to the pathogenesis of hypertension, dysfunctional nutrient-sensing signals appear to be a core mechanism behind hypertension of developmental origins." (PMID 35743061, 2022). "Additionally, we recently found that resveratrol therapy activated AMPK/SIRT1/PGC-1α pathway and protected offspring against hypertension and oxidative stress in another hypertension model of programming." (PMID 32053935, 2020). "Oral administration of a HMG-CoA reductase inhibitor, simvastatin, or an AMPK activator, metformin, to young HFD offspring reversed maternal HFD-programmed increase in AT1R and decreases in SIRT1, PGC-1α and TFAM; alleviated ROS production in RVLM, and attenuated sympathoexcitation and hypertension." (PMID 32446297, 2020). "Importantly, activation of the AMPK/SIRT1/PGC-1α pathway has been shown to reverse the programming process and prevent hypertension." (PMID 31766163, 2019). "The results indicate that in the Ang II-induced hypertension group, the expression levels of TNF, NFKB1, MAPK3, PTGS2, and RELA were markedly elevated compared to the control group, while the expression levels of HSP90AA1, HSP90AB1, PPARG, SIRT1, MAPK1, and PRKCA were significantly decreased." (PMID 39592923, 2024). "Second, we also identified that proximal tubular Sirt1 was downregulated by SGLT2/GLUT2-mediated intracellular signals in DN, which is in accordance with the finding that NAD and sirtuins are more influenced by high glucose-induced stimulation than hypertension-induced glomerulosclerotic injuries." (PMID 38587753, 2024). "Because NAMPT mainly regulates the SIRT family in the cardiovascular system, we used qRT-PCR to examine SIRT1-7 expression in MAECs and MOVAs transfected with the NAMPT plasmid and stimulated with Ang II to determine which SIRTs play the most important role in the development of hypertension." (PMID 33488923, 2020). "In the present study, we observed that hypertension-enhanced cardiac apoptosis led to high levels of SIRT1 and p-JNK, as well as low levels of PGC-1α in the hearts of untreated hypertensive rats, which might imply that the increase in the SIRT1 level may be a compensatory mechanism in hypertension." (PMID 36005430, 2022).
Hypertension (continued). "The purpose of this study was to examine age-related expression patterns of these signaling molecules, in particular MT, SIRT1, SIRT3, and SIRT6 in BE of subjects of different ages with and without arterial hypertension (AH)." (PMID 33143333, 2020).
renal fibrosis (103 papers, 2014 to 2026). A final common manifestation of a wide variety of chronic kidney diseases characterized by glomerulosclerosis and tubulointerstitial fibrosis. "In CKD induced by UUO, SIRT1-deficient mice exhibit more severe renal fibrosis and apoptosis compared with wild-type controls." (PMID 33362554, 2020). "Various mechanisms have been suggested to underlie the pathogenetic link between SIRT1 and the development of renal fibrosis." (PMID 32932720, 2020). "This was associated with SIRT1 upregulation and reduced phosphorylated Smad3, indicating partial reduction of renal fibrosis by low (25 mg/kg/day) RSV treatment." (PMID 31319485, 2019). "Additionally, luteolin has been found to reduce anemia caused by renal fibrosis through the SIRT1/FOXO3 pathway." (PMID 41334230, 2025). "Luteolin can reduce renal anemia caused by renal fibrosis by regulating SIRT1/FOXO3 pathway." (PMID 38403669, 2024). "A similar study demonstrated that GDNF‐modified ADSCs released GDNF‐rich exosomes, which could be transferred to renal fibrosis tissues and ameliorate peritubular capillary loss via the activation of the SIRT1/eNOS signaling pathway." (PMID 35441482, 2022). "To investigate this, we bred SIRT1 conditional knockout mice and examined whether SIRT1 deficiency in renal interstitial cells affects renal fibrosis." (PMID 33758176, 2021). "Recently, a growing body of evidence has proposed that the underlying molecular mechanisms for SIRT1 could potentially protect against renal fibrosis." (PMID 33758176, 2021). "Moreover, increased HIF-2α levels might be responsible for SIRT1 deficiency-induced severe renal fibrosis." (PMID 33758176, 2021). "Thus, the activation of the SIRT1/eNOS pathway may be the underlying mechanism by which GDNF-AMSC-exos enhance PTC density to protect against renal fibrosis." (PMID 32802201, 2020). "Since the SIRT1/Nrf2 pathway is known to influence these events, future work should extend the observation timeline to investigate the role of miR‐182‐5p in renal fibrosis and inflammatory infiltration." (PMID 41573363, 2026). "AST-IV increased SIRT1 expression when used on mouse podocytes, which reversed renal fibrosis and improved renal function in the experimental mice compared to mice that were not treated with AST-IV." (PMID 39859490, 2025). "The Atractylodes lancea and Magnolia officinalis combination alleviates tubular epithelial cell senescence and reduces proteinuria and renal fibrosis by restoring SIRT1 activity." (PMID 40552151, 2025). "AST-IV stimulated SIRT1 expression when used on mouse podocytes, which reversed renal fibrosis and improved renal function in the experimental mice compared to mice that were not treated with AST-IV." (PMID 39859490, 2025). "Activating SIRT1 can prevent renal fibrosis in patients with nephrolithiasis by inhibiting ferroptosis." (PMID 40303502, 2025). "In our study, OA treatment remarkably mitigated renal fibrosis and conserved kidney function by activating Sirt1 and suppressing the TGF-β/Smad3 pathway." (PMID 39687299, 2024). "It was observed that OA exhibits renoprotective properties and possesses anti-renal fibrosis effects, primarily attributed to its activation of Sirt1." (PMID 39687299, 2024). "Targeting SIRT1 can prevent or reduce age-related pathological changes in the renal tissue, including renal fibrosis." (PMID 39335456, 2024). "Collectively, SIRT1 exhibits beneficial effects in the management of renal fibrosis, suggesting its potential as a therapeutic target for this condition." (PMID 39335456, 2024). "In a unilateral ureteral obstruction (UUO) model of mice, knock-out of HIF-2α attenuated renal fibrosis through a mechanism involving sirtuin-1 (SIRT1)." (PMID 38275766, 2024).